STAT3 (signal transducer and activator of transcription 3)
Diseases named in the same sentence as STAT3 in open-access papers (continued):
Sharing a sentence is not in itself a finding about the gene and the disease.
cancer (continued). "The persistent activation of Stat3 is associated with cancer progression and resistance to therapy." (PMID 40492508, 2025). "Similarly, IL-6/IL-11 signaling in cancer-associated fibroblasts (CAFs) induces STAT3 activation, creating a protumorigenic niche that drives CRC growth and correlates with dismal outcomes." (PMID 40963625, 2025). "These chemokines activate STAT3, which is associated with cancer progression and poor prognosis." (PMID 40136652, 2025). "The excessive activation of JAK and its associated JAK/STAT signaling promotes cancer hallmarks such as proliferation, survival, and angiogenesis, in both the tumor and its surrounding environment, through the activation of STAT3, IL-6, IL-11, IL-22, IL-23, and interferon-γ (IFN-γ)." (PMID 40725854, 2025). "Notably, in certain cancer types, STAT3 has shown associations with reduced cancer progression and prolonged survival." (PMID 39843641, 2025). "Notably, its transcription is directly stimulated by activated Stat3, forming a pathological feed-forward loop in conditions such as cancer cachexia, where blocking Stat3 phosphorylation can mitigate muscle loss." (PMID 40724988, 2025). "In malignant tumors, persistent activation of STAT3 is often linked with adverse clinical outcomes." (PMID 40265014, 2025). "However, aberrant activation of the JAK2/STAT3 pathway is frequently detected in various tumors and has been implicated in the genesis, angiogenesis, and metastasis of many cancers." (PMID 40978029, 2025). "Our findings align with a recent study which demonstrated that cationic amphiphilic antihistamines induce lysosomal H+ efflux and cytosolic acidification in cancer cells, subsequently rendering cancer cells more susceptible to apoptosis through STAT3 inactivation." (PMID 39886963, 2025). "The association between STAT3 activation and chemoresistance highlights its importance as a therapeutic target, as inhibiting STAT3 could enhance cancer cell sensitivity to existing treatments." (PMID 40075607, 2025). "Moreover, hexokinase 2 (HK2), a rate-limiting enzyme in glycolysis, a transcriptional target of STAT3 and crucial for the Warburg effect, contributing to altered glucose metabolism in cancer cells, has been implicated in tamoxifen resistance." (PMID 39859445, 2025). "Additional studies have shown that melittin downregulates oncogenic pathways, including Akt, NF-κB, hypoxia-inducible factor 1-alpha (HIF-1α), Wnt, and signal transducer and activator of transcription 3 (STAT3), further supporting its ability to interfere with cancer-associated signaling networks." (PMID 40871040, 2025). "ERK1/2, p38 MAPK, and STAT3 signaling cascades have all been shown to mediate the transition from a quiescent fibroblast phenotype to a characteristic CAF phenotype associated with CAF-induced cancer progression, chemoresistance, and immune suppression." (PMID 40099972, 2025). "Although IL‐21 primarily signals via a STAT3, NF‐κB inhibition caused a lower proliferation in the presence of IL‐21, indicative of the complex interplay between these two pathways on NK cell proliferation, which has previously been observed in cancer." (PMID 39865344, 2025). "Furthermore, STAT3 has been linked to the development of acquired drug resistance, which poses a significant challenge in cancer treatment." (PMID 40860906, 2025). "Numerous studies have substantiated that STAT3 undergoes hyperactivation in the majority of human cancers, thereby regulating a multitude of genes linked to the immune evasion, drug resistance, metastasis, invasion, angiogenesis, proliferation, and survival of cancer cells." (PMID 38312603, 2024). "More specifically, the gene expression initiated by STAT3 has been linked with mechanisms causing the development of drug resistance, consisting of apoptotic resistance, upregulation of cancer growth, angiogenesis, invasiveness, and suppression of immune response." (PMID 37789138, 2024).
cancer (continued). "It is noted that HPV-associated cancers often exhibit elevated STAT3 activity." (PMID 39123466, 2024). "The IL-6/STAT3 signaling pathway is also essential in inflammation-associated cancers." (PMID 39061221, 2024). "Furthermore, clinical and cellular studies have confirmed that G6PD can activate signal transducer and activator of transcription 3 (STAT3), which is associated with poor outcomes and the migration and invasion of cancer cells." (PMID 38418897, 2024). "STAT3 is associated with cancer, cell proliferation, vascularization and immune evasion." (PMID 38185661, 2024). "However, aberrant activation of STAT3 has been implicated in cancer development, recurrence, and metastasis in addition to development of resistance to therapy." (PMID 38339245, 2024). "Research has found that RCC1 domain-containing protein 2 (HERC2) enhances the stemness of HCC cells and PD-L1-mediated immune escape, which is associated with the activation of the signal transducer and activator of transcription 3 (STAT3) pathway during the inflammation–cancer transition." (PMID 38780447, 2024). "CCL5 is associated with the STAT3 signaling pathway in several types of cancer." (PMID 39126553, 2024). "Activated STAT3 functions as a transcription factor targeting regulatory sequences of genes encoding pro-proliferation, pro-survival, and pro-angiogenic proteins in the nucleus thus aiding in the progression of OPMDs into cancer." (PMID 38803729, 2024). "This dual inhibition of both Akt and STAT3 signaling pathways by the combination treatment could be a potential mechanism underlying the enhanced inhibitory effects on cancer growth and metastasis observed in the study." (PMID 38388902, 2024). "Moreover, increased B cell infiltration and p-STAT3 expression in cancers are associated with poorer survival." (PMID 38245798, 2024). "Accelerated proliferation and spread of cancer cells can be caused by improper STAT3 activation." (PMID 39588118, 2024). "STAT3 was implicated with angiogenesis, cell migration, and drug resistance in cancers by promoting mitochondrial transcription and oxidative respiration that protect cancer cells against oxidative damage." (PMID 39000577, 2024). "Notably, BITC inhibited the phosphorylation of STAT3, a protein implicated in cancer cell growth and survival, whereas SFN’s inhibitory effects appeared to be STAT3-independent." (PMID 38919393, 2024). "Additionally, STAT3, a transcription factor, regulates genes associated with cancer cell survival, proliferation, angiogenesis, invasion, metastasis, drug resistance, and immune evasion." (PMID 39872609, 2024). "STAT3 is regarded as a promising target for colitis-associated cancers." (PMID 38967742, 2024). "While somatic STAT3 mutations are less common, they occur in specific cancers." (PMID 39104501, 2024). "Moreover, the upregulation of STAT3 has been implicated as a mechanism of drug resistance in a range of oncogene-addicted cancers." (PMID 39068158, 2024). "Most therapeutic development in this area has been directed at STAT3, though, as noted, other STATs may also play pathogenic roles in a variety of cancers." (PMID 38611065, 2024). "Along with NFκB, STAT3 has also been associated with cancer-related inflammation." (PMID 38571491, 2024). "In the context of cancer, increased p-STAT3 levels are associated with M2 polarization." (PMID 38467701, 2024). "In addition, IL-6 activates STAT3 and is associated with advanced-stage disease and reduced survival in cancer." (PMID 38539448, 2024). "Additionally, STAT3, a transcription factor associated with cancer development, acts as a crucial mediator of TNF pathway activation." (PMID 39586790, 2024). "Notably, elevated levels of STAT3 in a range of cancers have been linked to dismal prognostic outcomes." (PMID 39132168, 2024). "The JAKs/STAT3 pathway plays a pivotal role in oncogenic processes, governing cell proliferation, differentiation, invasion, metastasis, and inflammation associated with cancer." (PMID 38646539, 2024).
cancer (continued). "Several cytokines may be responsible of STAT activation and STAT3 has been closely associated with cancer aggressiveness in BC." (PMID 37979099, 2024). "This reduction may contribute to the promotion of TNFAIP8 and IL-6/STAT3, ultimately provoking inflammation and potentially increasing the risk of developing cancer." (PMID 37296861, 2023). "As an oncogene, STAT3 multiple phosphorylation sites are linked to different cancers." (PMID 36977736, 2023). "However, sustained activation of STAT3 causes various diseases, such as rheumatoid arthritis, atherosclerosis, stroke, myocardial ischemic injury, and cancer." (PMID 37240202, 2023). "This suggestion refers particularly to STAT3, which aberrant activation has been reported in nearly 70% of cancers, causing the continuous transcription of cell growth factors and anti-apoptotic molecules, thus playing a crucial role in maintaining cell growth and survival." (PMID 37570726, 2023). "In this work, we have generated novel ccRCC-derived cell lines to analyze the effects produced by STAT3 silencing and the impact caused by Y705 and S727 phosphorylation in cancer hallmarks such as proliferation, migration, colony formation, and anchorage-independent growth." (PMID 37945711, 2023). "Moreover, we demonstrated that CDK1-wildtype interacted with STAT3, while mutations CDK1-K33R or CDK1-K33Q both impeded the interaction with STAT3, resulting in reduced phosphorylation of STAT3, which caused the diminishment of cancer stemness." (PMID 37743465, 2023). "We have confirmed that alterations in the composition of oral bacteria can contribute to a reduction in SCFAs and the expression of the FFAR 2, resulting in an inflammatory response through the upregulation of TNFAIP8 and the IL-6/STAT3 pathway, ultimately increasing the risk of cancer onset." (PMID 37296861, 2023). "However, it is well known that dysregulation and constitutive activation of STAT3 are associated with human diseases, including cancer." (PMID 37287455, 2023). "Similar findings were observed in our study, STAT3 inhibition could effectively reverse the cancer-promoting function of TRIM29 deficiency in ESCC." (PMID 37365152, 2023). "The cytokine most often implicated in STAT3-driven cancer pathogenesis is IL-6." (PMID 38022653, 2023). "Aberrant STAT-3 activation has also been linked to cancer hallmarks and poor patient outcomes." (PMID 37175040, 2023). "Silibinin is a direct STAT3 targeting agent, which can not only reduce therapy-associated nephrotoxicity, neurotoxicity and cardiotoxicity in preclinical models but also has the potential to reverse cancer cell drug resistance." (PMID 36911202, 2023). "STAT3 has a role in both extrinsic and intrinsic pathways linked to cancer." (PMID 37298889, 2023). "Because of this association, STAT3 is considered a promising candidate target for cancer treatment." (PMID 37928418, 2023). "Importantly, ROR1/STAT3 expression was also detected in cancer-associated fibroblasts or CAFs, which are often associated with worse disease prognosis in many cancers." (PMID 37400436, 2023). "Given the pathogenic effect of activated STAT3 after forming a complex with Hsp110 in the progression of cancer and the advantage of PPI inhibitors in the treatment of diseases, we preliminarily evaluated their activities on the downstream STAT3 pathway in HPAECs." (PMID 37978368, 2023). "Multiple studies have implicated STAT3 in differential tissue expression in multiple cancers." (PMID 36977736, 2023). "However, immune-related cancer hallmark gene sets, such as IL6_JAK_STAT3_SIGNALING, INTERFERON_ ALPHA_RESPONSE and INFLAMMATORY_RESPONSE, were significantly enriched on the negative side of the NED signature." (PMID 37199872, 2023).
cancer (continued). "Specifically, we hypothesized that STAT3 changes mediated by RT play a central role in the protective effects of RT during cancer-induced muscle atrophy and strength loss." (PMID 35847939, 2022). "Similarly, a decrease in IL-6-induced STAT3 mitochondrial localisation leads to mitochondrial oxidative stress, loss of mitochondrial membrane potential, and subsequent apoptosis of cancer cells." (PMID 36429126, 2022). "IL-6 can activate AP-1 and STAT3 TFs; both factors are implicated with dual behaviors in cancer." (PMID 36544764, 2022). "In most human cancers, over-activation of STAT3 is usually associated with poor clinical prognosis." (PMID 35401187, 2022). "We hypothesized that RT may protect against the excessive activation of STAT3 by the overabundance of IL-6 and oxidative stress during cancer-induced muscle atrophy and strength loss." (PMID 35847939, 2022). "However, considerable evidence suggests that silymarin can reverse STAT-3-associated cancer drug resistance by down-regulating its gene expression." (PMID 36014565, 2022). "Moreover, IL-6/IL-11 activates STAT3 in cancer-associated fibroblasts (CAFs) to promote CRC progression and poor prognosis." (PMID 35783510, 2022). "Finally, mounting evidence suggests that high hTERT activity is tightly associated with Stat3 activation, cancer progression and poor outcomes, and Stat3 knock-out downregulates hTERT expression." (PMID 35681623, 2022). "And it has been reported that persistent activation of STAT3, and the phosphorylation level of STAT3 may be associated with the poor prognosis of cancer." (PMID 35115495, 2022). "In addition to cancer cells, STAT3 expression in senescent cancer‐associated fibroblasts (CAFs) can improve the viability of cancer cells, which is associated with the senescence‐associated secretory phenotype." (PMID 35356799, 2022). "These two main pathways for inflammation are activated by the most important cancer risk factors, and a majority of gene products linked to inflammation, survival, proliferation, invasion, angiogenesis, and metastasis is controlled by NF-κB and STAT3." (PMID 36613784, 2022). "CBD modulates mitochondrial Ca2+ buffering and function (mitochondrial swelling, ROS production) and reduces the expression of mitochondrial-associated proteins prohibitin and STAT3 (signal transducer and activator of transcription 3) in cancer cells, thus intensifying cell stress and apoptosis." (PMID 35456540, 2022). "Among them, STAT3 is involved in cell proliferation, differentiation, apoptosis, and inflammatory responses, and also STAT3-related signaling pathways are aberrant over-activated in many types of cancer and are strongly associated with poor patient prognosis." (PMID 36291659, 2022). "Abnormal activation of the STAT3 pathway is linked to cancer development." (PMID 35267408, 2022). "Although overexpression studies have associated miR-21 expression with Stat3 signaling, it remains unknown whether a functional interaction between these molecules contributes to tumorigenesis in autochthonous cancer models." (PMID 35053428, 2022). "Whilst Stat3 regulates many genes and processes, its regulation of normal and cancer stem cells has been linked particularly with direct transcriptional activation of ΔNp63, itself a regulator of normal and CSCs and associated specifically with basal-like TNBC." (PMID 36017196, 2022). "In another study, prostatic epithelial cell lines infected with C. acnes responded via activation of transcription factors such as NF-κB and STAT3, which are associated with cellular proliferation and tumor growth in various cancers, such as PCa and colon cancer." (PMID 35065652, 2022). "The JAK/STAT3 pathway is a critical signaling pathway implicated in many cancer types." (PMID 36428556, 2022).
cancer (continued). "Although these proteins are not surface markers and are therefore difficult for analysis, they helped to define two separate MDSC groups, CD33+ HLA-DR−/low STAT3+ and CD11b+ HLA-DR−/low c/EBPβ+, which provided novel diagnostic and therapeutic tools for cancer immunotherapy." (PMID 35053426, 2022). "Even though gain‐of‐function (GOF) mutations of STAT5B were reported in a minor fraction (3.6%) of CTCL patients, our WES data were negative for GOF JAK–STAT mutations, but we consistently found copy number gains of STAT3/5 representing a cancer genome hallmark for the majority of L‐CTCL patients." (PMID 36341492, 2022). "Therefore, our study only suggests, in the absence of an autophagic flux experiment, that the phosphorylation of STAT3 in response to exacerbated IL-6 and ROS formation seems to be associated with autophagy activation during cancer cachexia." (PMID 35847939, 2022). "STAT3 has been implicated in cell proliferation and human cancers." (PMID 34976224, 2022). "Moreover, recent studies reported that the IL-6/JAK/STAT3 signaling pathway is associated with glycolysis metabolism of cancer cells." (PMID 35090515, 2022). "In addition, cancer-associated fibroblasts (CAFs) can induce PD-L1 expression on neutrophils to impair T-cell function by IL-6 - Stat3 signaling pathway." (PMID 36016960, 2022). "Moreover, in hepatoblastoma, lncPVT1 overexpression is associated with high levels of p-STAT3, thus promoting proliferation and cancer progression." (PMID 34754096, 2022). "SOX2, UBTF, NFE2L2, TCF3 and STAT3 were underlined as common transcriptional factors, which are responsible for the upregulation of genes involved in processes of the epithelial–mesenchymal transition, cancer stemness, invasion and migration of GBM." (PMID 36231068, 2022). "In cancer-associated fibroblasts (CAFs), CuI (50 nM) promoted apoptosis with inhibition of p-STAT3." (PMID 36355554, 2022). "Therefore, whereas analyses of the expression and function of molecules associated with STAT3 activation can assess the local and steady-state malignant potential of a cancer, they are insufficient to predict the stage or detailed course of a cancer." (PMID 36010693, 2022). "Changes in the interactions with pSTAT3 could be caused by increased total levels of phosphorylated Tyr705 STAT3 following stimulation, which has been previously demonstrated in both DCs and cancer cells after type 1 IFN." (PMID 36375639, 2022). "Accumulating evidence has revealed that CaMKIIγ functions as an important molecular switch in several oncogenic signaling pathways, including nuclear factor kappa B (NF-κB), Wnt/β-catenin, ERK, AKT, and STAT3, and thus is closely implicated in the pathogenesis of cancer." (PMID 36432068, 2022). "To investigate the role of LCN2 in cancer development driven by chronic inflammation, we analyzed the molecular mechanisms associated with cell survival and apoptosis that are downstream of the NF-kB/STAT3 pathway by Western blotting." (PMID 35470375, 2022). "Because STAT3 promotes the expression of genes involved in proliferation, survival, angiogenesis, immune evasion, and metastasis, the degree of STAT3 expression is associated with the prognosis of patients in various cancers." (PMID 36551576, 2022). "Let-7c-5c acts as a tumor suppressor in human cancers by affecting the proliferation and apoptosis of cancer cells and inhibiting STAT3 expression, which was previously shown to be associated with the proliferation and differentiation of osteoblasts in a rat model of RA." (PMID 35796900, 2022). "STAT3, a key signaling pathway that regulates cell growth, proliferation, and survival, functions as an important mediator linked to chronic inflammation and cancer." (PMID 34684488, 2021). "Similarly, a single-nucleotide polymorphism (SNP) in FGFR4 (rs351855, causing G388R substitution) is associated with many types of cancers and increases the recruitment and activation of STAT3, thereby enhancing cancer progression." (PMID 33535617, 2021).